MIR4703 (microRNA 4703)
Synonyms: hsa-mir-4703
Gene: MicroRNA gene on chromosome 13 (51,552,589 to 51,552,667, forward strand). Ensembl gene ENSG00000266611.
Homologues: Orthologues: chimpanzee MIR4703 (100% identical).